NPEPL1 (aminopeptidase like 1)
Description:
Probably catalyzes the removal of unsubstituted N-terminal amino acids from various peptides.
Synonyms: FLJ11583; bA261P9.2; LOC124904942
Tractability: Small molecule: a drug acting on it is in phase 2 or 3 trials. PROTAC: ubiquitination databases record sites on it; its protein half-life has been measured.
Gene: Protein-coding gene on chromosome 20 (58,689,131 to 58,719,238, forward strand). Ensembl gene ENSG00000215440.
Subcellular location (Human Protein Atlas): Nucleoplasm; Cytosol
Gene Ontology:
Molecular function: manganese ion binding; metal ion binding; metalloaminopeptidase activity
Biological process: proteolysis
Cellular component: nucleus; cytoplasm
Genetic constraint (gnomAD): Loss-of-function variants: 39 observed, 39.58 expected, observed/expected ratio (o/e) 0.99, 90% interval 0.76 to 1.29. The synonymous counts are far from expectation, so gnomAD's model fits this gene poorly and the ratio says little. Missense variants: 693 observed, 615.48 expected, observed/expected ratio (o/e) 1.13, 90% interval 1.06 to 1.2. Synonymous variants: 355 observed, 280.2 expected, observed/expected ratio (o/e) 1.27, 90% interval 1.16 to 1.38.
Homologues: Orthologues: chimpanzee NPEPL1 (99% identical), dog NPEPL1 (96% identical), guinea pig NPEPL1 (95% identical), mouse Npepl1 (95% identical), rat Npepl1 (94% identical), pig NPEPL1 (85% identical), macaque NPEPL1 (83% identical), tropical clawed frog npepl1 (83% identical), zebrafish npepl1 (81% identical), rabbit NPEPL1 (69% identical), Drosophila melanogaster grsm (62% identical), Caenorhabditis elegans lap-1 (42% identical). Paralogues in human: LAP3 (24% identical).
Diseases named in the same sentence as NPEPL1 in open-access papers:
NPEPL1 is named in the same sentence as 18 diseases in open-access papers, as found by Europe PMC text mining. Sharing a sentence is not in itself a finding about the gene and the disease. The quoted sentences say what the papers report.
breast carcinoma (4 papers, 2012 to 2023). "In the previous study, NPEPL1 had functions in the development and progression of prostate cancer and breast cancer." (PMID 36816355, 2023). "NPEPL1 was confirmed to be a potential direct target of miR-19a in a breast cancer study and miR-19a was up-regulated in primary motor cortex and hippocampus in the brain of amyotrophic lateral sclerosis mice at late disease stage." (PMID 33372590, 2020). "Among these candidate targets, IMPDH1 and NPEPL1 were identified as novel direct targets of miR-19a in the MCF-7 breast cancer cells." (PMID 22952885, 2012). "In order to examine the effects of the IMPDH1 and NPEPL1 genes on growth suppression of breast cancer cells, the GFP expression vectors bearing the IMPDH1 or NPEPL1 gene were transfected into MCF-7 cells by electroporation." (PMID 22952885, 2012).
colorectal cancer (4 papers, 2021 to 2023). A primary or metastatic malignant neoplasm that affects the colon or rectum. "There are few reports available on aminopeptidase-like 1 (NPEPL1) and shroom family member 3 (SHROOM3); however, Shen and colleagues found that NPEPL1 can act as an oncogene in colorectal cancer." (PMID 36330441, 2022). "It regulated NPEPL1 expression by sponging miR-19a-3p and contributed to the growth and metastasis in colorectal cancer cells." (PMID 35083240, 2021). "Expression of NPEPL1 has been reported to be involved in prostate, breast, and colorectal cancers." (PMID 36816355, 2023).
Clear Cell Renal Cell Carcinoma (1 paper, 2023). "However, the role and mechanism of NPEPL1 in clear cell renal cell carcinoma (ccRCC) are unclear." (PMID 36816355, 2023).
prostate carcinoma (1 paper, 2023). A carcinoma that arises from epithelial cells of the prostate gland. "NPEPL1 has been reported as one of the prognostic markers of destructive resistance prostate cancer and appeared to be useful in predicting the recurrence-free survival of patients." (PMID 36816355, 2023).
thyroid carcinoma (1 paper, 2023). "Compared to normal tissues, NPEPL1 expression was higher in 13 types of cancer, including KIRC, and lower in thyroid carcinoma and kidney chromophobe." (PMID 36816355, 2023).
cancer (4 papers, 2021 to 2023). A tumor composed of atypical neoplastic, often pleomorphic cells that invade other tissues. "The data suggested that NPEPL1 was differentially expressed in different tissues and in different types of cancer in the same tissue." (PMID 36816355, 2023). "First, we found that mRNA NPEPL1 was differentially expressed between normal tissues and tumor tissues in different organs via pan-cancer analysis." (PMID 36816355, 2023). "It is unclear whether NPEPL1 plays a role in PCa and other cancers." (PMID 33671634, 2021). "NPEPL1 is a probable aminopeptidase and it has been found to form a fusion with STX16 in cancer tissue." (PMID 33827643, 2021).
tumor (4 papers, 2012 to 2023). "As miR-19a was expressed at a significantly highly level in MCF-7 cells, it is considered that the IMPDH1 and NPEPL1 proteins might function as tumor suppressors if they are associated with tumorigenesis under the control of miR-19a." (PMID 22952885, 2012). "Above all, NPEPL1 expression regulated the distribution of immune cells in tumor tissues through immune checkpoints, which affected the occurrence and development of ccRCC." (PMID 36816355, 2023). "NPEPL1 expression was higher in ccRCC tissues, and the expression increased gradually with the increase in tumor grade and stage." (PMID 36816355, 2023). "The coexpression analysis found that NPEPL1 altered tumor characteristics by interacting with related genes." (PMID 36816355, 2023). "We classified the 539 patients in the TCGA-KIRC cohort into high and low NPEPL1 groups according to the median expression of NPEPL1 in tumor tissue as the cutoff." (PMID 36816355, 2023). "The expression of NPEPL1 in different features was detected to clarify its role in ccRCC, in which the expression was higher in tumor tissues." (PMID 36816355, 2023). "The HPA database also confirmed that the protein of NPEPL1 was more detectable in tumor tissue." (PMID 36816355, 2023). "NPEPL1 proteins might function as tumor suppressors in tumorigenesis under the control of the miR-19a microRNA, although this has also not been consistently proved, so the effect of the overdose of this gene also remains elusive." (PMID 25710380, 2015). "Moreover, LINC00342 functioned as a tumor promoter by sponging miR-19a-3p and releasing NPEPL1." (PMID 33588834, 2021). "However, the pro-tumor effects of LINC00342 were reversed by NPEPL1 knockdown (P < 0.01)." (PMID 33588834, 2021). "Functional analyses revealed that the overexpression of LINC00342 partly overturned the tumor suppressive effects of NPEPL1 knockdown in CRC, indicating that LINC00342 accelerated CRC progression, at least in part, through regulating the expression of NPEPL1 by serving as a sponge of miR-19a-3p." (PMID 33588834, 2021).
NPEPL1 also shares sentences with these, for which no sentence is quoted: gastrointestinal stromal tumor (2 papers); acute myeloid leukemia (1); adenoma (1); Allergy (1); Alzheimer disease (1); amyotrophic lateral sclerosis (1); asthma (1); legionellosis (1); Obesity (1); pertussis (1); rectal cancer (1).